MTFR1 (mitochondrial fission regulator 1)
Description:
May play a role in mitochondrial aerobic respiration. May also regulate mitochondrial organization and fission (By similarity).
Synonyms: CHPPR; FAM54A2; KIAA0009
Tractability: Antibody: its Gene Ontology location is reachable by antibodies, with high confidence. PROTAC: ubiquitination databases record sites on it; its protein half-life has been measured.
Gene: Protein-coding gene on chromosome 8 (65,644,684 to 65,771,261, forward strand). Ensembl gene ENSG00000066855.
Subcellular location: Mitochondrion
Subcellular location (Human Protein Atlas): Mitochondria; Cytosol
Gene Ontology:
Molecular function: protein binding
Biological process: aerobic respiration; mitochondrial fission; mitochondrion organization
Cellular component: cytosol; mitochondrion; plasma membrane
Genetic constraint (gnomAD): Loss-of-function variants: 18 observed, 30.17 expected, observed/expected ratio (o/e) 0.6, 90% interval 0.41 to 0.88. The upper end of that interval is the gene's LOEUF score, 0.88, which puts it in group 3 of 6, group 1 being the genes least tolerant of losing a copy. Missense variants: 323 observed, 363.25 expected, observed/expected ratio (o/e) 0.89, 90% interval 0.81 to 0.98. Synonymous variants: 126 observed, 124.61 expected, observed/expected ratio (o/e) 1.01, 90% interval 0.87 to 1.17.
Homologues: Orthologues: chimpanzee MTFR1 (99% identical), macaque MTFR1 (91% identical), guinea pig MTFR1 (81% identical), rabbit MTFR1 (79% identical), dog MTFR1 (78% identical), rat LOC120101654 (77% identical), mouse Mtfr1 (76% identical), pig MTFR1 (76% identical), tropical clawed frog mtfr1 (60% identical), zebrafish mtfr1 (44% identical). Paralogues in human: MTFR2 (33% identical), MTFR1L (23% identical).
Diseases named in the same sentence as MTFR1 in open-access papers:
MTFR1 is named in the same sentence as 21 diseases in open-access papers, as found by Europe PMC text mining. Sharing a sentence is not in itself a finding about the gene and the disease. The quoted sentences say what the papers report.
lung adenocarcinoma (5 papers, 2021 to 2025). A carcinoma that arises from the lung and is characterized by the presence of malignant glandular epithelial cells. "consistently reported that MTFR1, which was overexpressed in lung adenocarcinoma and associated with unfavorable prognosis in cancer patients, could enhance the proliferation, invasion, migration, and glycolysis of lung adenocarcinoma cells." (PMID 40620061, 2025). "miR-29c-3p suppresses the activity of Mitochondrial fission regulator 1 (MTFR1), thereby inhibiting the progression of lung adenocarcinoma via the AMPK/mTOR signaling pathway." (PMID 39712244, 2024).
myocardial infarction (5 papers, 2015 to 2022). Gross necrosis of the myocardium, as a result of interruption of the blood supply to the area, as in coronary thrombosis. "In the context of cardiac disorders, NFAT4 has been shown to regulate miR-324-5p/Mtfr1 axis to enhance mitochondrial fission and cardiomyocyte apoptosis and aggravate pathogenic events in the myocardial infarction." (PMID 36035118, 2022). "Overexpression of miR-324-5p resulted in decreased Mtfr1 expression levels, mitochondrial fission, cardiomyocytes apoptosis and myocardial infarction." (PMID 26633713, 2015). "Mtfr1 can regulate mitochondrial fission and apoptosis in cardiomyocytes and knockdown of Mtfr1 in mice showed a reduced myocardial infarction sizes upon ischemia injury in vivo." (PMID 26633713, 2015). "MiR-324-5p and Mtfr1 have complementary expression patterns during cardiomyocytes apoptosis and myocardial infarction." (PMID 26633713, 2015). "Mtfr1 is a direct target of miR-324-5p, and miR-324-5p attenuates mitochondrial fission, cardiomyocyte apoptosis and myocardial infarction by suppressing Mtfr1 translation." (PMID 26633713, 2015). "Knockdown of Mtfr1 in mice exhibits a reduced mitochondrial fission, apoptosis and myocardial infarction sizes upon I/R injury." (PMID 26633713, 2015). "MiR-324-5p inhibits mitochondrial fission, apoptosis and myocardial infarction through downregulating Mtfr1." (PMID 26633713, 2015). "NFAT4 through miR-324-5p/Mtfr1 axis could increase mitochondrial fission, cardiomyocyte apoptosis and myocardial infarction." (PMID 36035118, 2022). "Moreover, miR-324-5p was shown to inhibit mitochondrial fission, apoptosis, and myocardial infarction through downregulation of Mtfr1, whereas MR is expressed in cardiac myocytes, and its activation is associated with myocardial hypertrophy and fibrosis." (PMID 35563683, 2022). "Actually, MTFR1 knockdown reduced myocardial infarction sizes in mice." (PMID 28827743, 2017). "To understand the pathophysiological role of Mtfr1, we detected whether Mtfr1 was involved in the pathogenesis of myocardial infarction in the animal model." (PMID 26633713, 2015). "Knocking down Mtfr1 suppresses mitochondrial fission, apoptosis and myocardial infarction." (PMID 26633713, 2015). "In addition, we demonstrated that miR-324-5p is responsible for the downregulation of Mtfr1, and modulation of miR-324-5p levels also affects mitochondrial fission, apoptosis and myocardial infarction." (PMID 26633713, 2015). "Also, knockdown of Mtfr1 in mice exhibit a reduced myocardial infarction sizes upon myocardial ischemia/reperfusion (I/R) injury in vivo." (PMID 26633713, 2015).
lung carcinoma (4 papers, 2023 to 2024). "Consistently, the Lung cancer explorer (LCE) database analysis also revealed that patients with high MTFR1 expression had an unfavourable prognosis." (PMID 38170222, 2024). "miR-29c-3p expression was found downregulated in lung cancer cells and inversely correlated to MTFR1 levels." (PMID 36827549, 2023). "The miR-29 family advances lung cancer progression through the AMPK/mTOR signaling pathway by negatively regulating MTFR1, while miR-15a-5p inhibits metastasis and lipid metabolism in NSCLC." (PMID 38001571, 2023). "Upregulation of MTFR1 by lentiviral-mediated overexpression affected the mitochondrial dynamics balance in lung cancer cells, increasing mitochondrial fission and leading to stimulation of proliferation, invasion, and migration of cancer cells both in vitro and in vivo in a xenograft model." (PMID 36827549, 2023). "An important role as mitochondrial fission regulator is played by MTFR1, a mitochondrial protein found overexpressed in lung cancer cell lines and tissues, and positively correlated with adverse clinicopathological features as well as poor overall survival of cancer patients." (PMID 36827549, 2023). "Interestingly, overexpression of MTFR1 promoted aerobic glycolysis by increasing glucose consumption and lactate production, exerting its oncogenic function by targeting the AMPK/mTOR signaling pathway in lung cancer cells." (PMID 36827549, 2023).
age (1 paper, 2025). A temporal measurement of the time period elapsed since an identifiable point in the life cycle of an organism. "One of the most significantly upregulated genes include MTFR1 (mitochondrial fission regulator 1), which is known to protect against oxidative stress, but is also associated with age-associated cognitive decline." (PMID 41345807, 2025).
breast carcinoma (1 paper, 2021). "In addition, MTFR2, which belongs to the same family as MTFR1, promotes the progression of breast cancer and oral squamous carcinoma when its expression is dysregulated." (PMID 34926459, 2021).
head and neck squamous cell carcinoma (1 paper, 2021). A squamous cell carcinoma that arises from any of the following anatomic sites: lip and oral cavity, nasal cavity, paranasal sinuses, pharynx, larynx, and salivary glands. "In addition, MTFR1 has a vital function in oral squamous cell carcinoma, acute myocardial infarction (AMI) and head and neck squamous cell carcinoma (HNSCC)." (PMID 34926459, 2021).
laryngeal carcinoma (1 paper, 2019). Carcinoma that arises from the laryngeal epithelium. "Assessment of these genes in clinical sub-cohorts of TCGA indicated that early stage tongue (MTFR1, C8ORF33, OTUD6B) and laryngeal cancers (TWISTNB, KLHL13 and UBE2Q1) were defined by distinct prognosticators." (PMID 31310629, 2019).
tongue cancer (1 paper, 2019). A malignant neoplasm affecting the tongue. "Early stage tongue cancer patients were significantly classified into patients with poor/good survival based on alterations in AP2M1, CTBP1, and MTFR1 all of whom were associated with prognosis in other studies." (PMID 31310629, 2019).
cancer (4 papers, 2021 to 2025). A tumor composed of atypical neoplastic, often pleomorphic cells that invade other tissues. "Preliminary evidence suggested that MTFR1 was involved in cancer progression as a carcinogenic gene." (PMID 38170222, 2024). "However, to date, only a few studies have used bioinformatic analyses to assess whether MTFR1 is involved in the development of cancers." (PMID 34926459, 2021). "In addition, we discovered that miR-29c-3p was a direct upstream target of MTFR1 and could inhibit the cancer-promoting functions of MTFR1." (PMID 34926459, 2021). "To assess the impact of MTFR1 on the migratory and invasive abilities of LUAD cancer cells, we performed Transwell and wound-healing assays." (PMID 34926459, 2021). "However, because MTFR1 exerts robust cancer-promoting effects on LUAD, further investigation is required to identify proteins that interact with MTFR1 to exercise such effects." (PMID 34926459, 2021).
tumour (3 papers, 2021 to 2025). "In keeping with the importance of tumour-associated immune cells, our data revealed that MTFR1 expression also correlated with LAC stromal cells and immune cells, as well as immune cell markers, indicating that MTFR1 might play a vital role in LAC progression and immune escape." (PMID 38170222, 2024). "Compared with those in the adjacent normal lung tissues, the protein and mRNA levels of MTFR1 were considerably elevated in LUAD tumour tissues." (PMID 34926459, 2021). "A tumour xenograft-harbouring nude mouse model and a tail-vein injection-induced metastasis model were constructed to assess the in vivo impacts of MTFR1 on tumour growth and metastasis." (PMID 34926459, 2021). "High MTFR1 expression was significantly related to the clinical stage (p = 0.007), lymph node metastasis (p = 0.016) and tumour size (p = 0.023)." (PMID 34926459, 2021). "Furthermore, HE staining and IHC analysis were performed on tumour xenografts to analyse Ki-67 and MTFR1 expressions." (PMID 34926459, 2021). "Altogether, the results indicated that MTFR1 promoted LUAD tumour growth and metastasis in vivo." (PMID 34926459, 2021). "In conclusion, MTFR1 serves as a strong tumour-promoting factor in LUAD, and targeting MTFR1 may provide a better disease outcome for patients with LUAD." (PMID 34926459, 2021).
cardiac diseases (1 paper, 2015). "Our study defines the NFAT4/ miR-324-5p/Mtfr1 axis, which participates in the regulation of mitochondrial fission and cardiomyocyte apoptosis, and suggests potential new treatment avenues for cardiac diseases." (PMID 26633713, 2015). "Our study suggests a potential signal pathway of miR-324-5p and Mtfr1 for cardiac diseases and they will be intriguing targets for therapeutic intervention." (PMID 26633713, 2015).
infection (1 paper, 2015). The state of being infected such as from the introduction of a foreign agent such as serum, vaccine, antigenic substance or organism. "Studies carried out with MMTV(C3H) Env-pseudotyped MLV viruses showed that mTfR1 is used by MMTV to initiate infection of mouse cells." (PMID 25980759, 2015). "Mouse transferrin receptor 1 (mTfR1) is used by MMTV to initiate infection of murine cells." (PMID 25980759, 2015).
MTFR1 also shares sentences with these, for which no sentence is quoted: Azoospermia (1 paper); cognitive decline (1); ischemia (1); lymph node metastasis (1); male infertility (1); myocardial hypertrophy (1); oral squamous cell carcinoma (1); prostate carcinoma (1); rhabdoid tumor (1).